WDR64 (WD repeat domain 64)
Synonyms: FLJ32978
Tractability: PROTAC: ubiquitination databases record sites on it.
Gene: Protein-coding gene on chromosome 1 (241,652,278 to 241,802,777, forward strand). Ensembl gene ENSG00000162843.
Subcellular location: Cytoplasm; Cell projection, cilium, flagellum
Gene Ontology:
Cellular component: cytoplasm; motile cilium
Genetic constraint (gnomAD): Loss-of-function variants: 94 observed, 121.97 expected, observed/expected ratio (o/e) 0.77, 90% interval 0.65 to 0.92. The upper end of that interval is the gene's LOEUF score, 0.92, which puts it in group 3 of 6, group 1 being the genes least tolerant of losing a copy. Missense variants: 1,128 observed, 1,243.9 expected, observed/expected ratio (o/e) 0.91, 90% interval 0.86 to 0.95. Synonymous variants: 412 observed, 430.6 expected, observed/expected ratio (o/e) 0.96, 90% interval 0.88 to 1.04.
Homologues: Orthologues: chimpanzee WDR64 (98% identical), macaque WDR64 (96% identical), dog WDR64 (83% identical), pig WDR64 (81% identical), mouse Wdr64 (80% identical), rat Wdr64 (80% identical), guinea pig WDR64 (72% identical), Drosophila melanogaster WDY (15% identical), Caenorhabditis elegans sel-10 (8% identical), zebrafish si:ch211-154o6.3 (4% identical). Paralogues in human: EFCAB8 (16% identical), WDR49 (16% identical), FBXW7 (9% identical), TRAF7 (8% identical), FBXW11 (8% identical), BTRC (7% identical), FBXW8 (7% identical), WDR86 (6% identical), FBXW9 (6% identical), WDR54 (4% identical), FBXW12 (4% identical), PAAF1 (4% identical), and 2 more.